TMEM144 (transmembrane protein 144)
Synonyms: FLJ11155; SLC35G7
Tractability: Antibody: UniProt predicts a signal peptide or a membrane-spanning region.
Gene: Protein-coding gene on chromosome 4 (158,201,604 to 158,255,416, forward strand). Ensembl gene ENSG00000164124.
Subcellular location: Membrane
Subcellular location (Human Protein Atlas): Mitochondria
Gene Ontology:
Molecular function: protein binding; carbohydrate transmembrane transporter activity
Biological process: carbohydrate transmembrane transport
Cellular component: membrane
Genetic constraint (gnomAD): Loss-of-function variants: 28 observed, 28.17 expected, observed/expected ratio (o/e) 0.99, 90% interval 0.74 to 1.36. The upper end of that interval is the gene's LOEUF score, 1.36, which puts it in group 5 of 6, group 1 being the genes least tolerant of losing a copy. Missense variants: 305 observed, 322.8 expected, observed/expected ratio (o/e) 0.94, 90% interval 0.86 to 1.04. Synonymous variants: 124 observed, 112.85 expected, observed/expected ratio (o/e) 1.1, 90% interval 0.95 to 1.28.
Homologues: Orthologues: chimpanzee TMEM144 (99% identical), macaque TMEM144 (98% identical), pig TMEM144 (91% identical), rabbit TMEM144 (90% identical), rat Tmem144 (87% identical), mouse Tmem144 (86% identical), dog TMEM144 (84% identical), guinea pig TMEM144 (83% identical), tropical clawed frog tmem144 (69% identical), zebrafish tmem144a (64% identical), zebrafish tmem144b (54% identical), Caenorhabditis elegans R144.6 (40% identical), and 5 more.
Diseases named in the same sentence as TMEM144 in open-access papers:
TMEM144 is named in the same sentence as 6 diseases in open-access papers, as found by Europe PMC text mining. Sharing a sentence is not in itself a finding about the gene and the disease. The quoted sentences say what the papers report.
chordoma (1 paper, 2014). Chordomas are rare malignant tumors arising from embryonic remnants of the notochord in axial skeleton. "We found ALG11 and PPP2CB to be up- and TMEM144 to be differentially regulated in large physaliferous MUG-Chor1 cells, hence being putative effector genes for chordoma cell development." (PMID 24503940, 2014).
cancer (3 papers, 2014 to 2025). A tumor composed of atypical neoplastic, often pleomorphic cells that invade other tissues. "However, Prentice and colleagues linked TMEM144 to the regulation of kisspeptin that itself seems to be involved in cancer by suppressing metastasis due to inhibition of cancer cell motility." (PMID 24503940, 2014). "TMEM144, enriched in monocytes and dendritic cells, is linked to M2 macrophage-driven tumour progression, and CD84 serves as a surface marker for myeloid-derived suppressor cells (MDSCs), facilitating their detection in cancer tissues." (PMID 40340807, 2025). "The six upregulated genes (FCGR3A, LPAR5, MATK, MNDA, TMEM144, and CD84) play key immunomodulatory roles in cancer progression and metastasis." (PMID 40340807, 2025).
TMEM144 also shares sentences with these, for which no sentence is quoted: tumor (3 papers); head and neck cancer (1); oral cancer (1); renal cell carcinoma (1).